IL1B (interleukin 1 beta)
Diseases named in the same sentence as IL1B in open-access papers (continued):
Sharing a sentence is not in itself a finding about the gene and the disease.
tumor (continued). "Importantly, upregulated IL‐1β expression was associated with attenuated cytotoxicity of CAR‐T cells and reduced CD8+granzyme B distribution in patient‐derived tumor tissues." (PMID 37009412, 2023). "We observed elevated IL-1β production in tumor-bearing mice with microbiota alteration, although the detailed mechanism remains unknown." (PMID 37400621, 2023). "Furthermore, these DC/tumor fusion cells produced higher levels of TNF-α, IL-1β and IL-6 than DCs cultured alone or simply mixed with tumor cells." (PMID 37419930, 2023). "Importantly, IL-1β neutralization restored the STC in the tumor-bearing mice fed with either normal water or ABX water." (PMID 37400621, 2023). "The activated p38 MAPK, in turn, promotes the production of cytokines (TGFβ and TNFα) and interleukins (IL-6, IL-8, and IL-1β) within the tumor microenvironment, all of which are known to play a role in promoting tumor growth, angiogenesis, invasion, and metastasis." (PMID 36993955, 2023). "Whereas this effect was mostly dependent on NLRP3, not Aim2, inflammasome, since knockout of Nlrp3, Asc, or caspase‐1 but not Aim2 through CRISPR‐Cas9 technique in DC2.4 cells markedly decreased the protein level of IL‐1β induced by the Arf1‐ablated tumor cells." (PMID 37786300, 2023). "IL-1β has been shown to have both pro- and anti-tumor effects." (PMID 37298187, 2023). "Next, we asked whether the IL‐1β blockade could reinvigorate the suppressed immune responses and synergistically inhibit the tumor growth with ICB in syngeneic mice models." (PMID 37009412, 2023). "Previous studies showed that tumor cell-derived hyaluronan and soluble CD44 could induce the expression of IL-1β in monocyte and macrophages in primary tumor, respectively." (PMID 37443052, 2023). "IL-1β increases monocyte recruitment via tumor cell expression of MCPs." (PMID 37733448, 2023). "Besides, a raised level of MIC-1 mediated by IL-1β in serum contributes to actin reorganization of tumor cells through activating FAK-RhoA signaling, thus reducing adhesion at an early stage." (PMID 36117852, 2022). "Ershaid and associates investigated the relationship between pyroptosis and TIME in BC, proposing that immune cell collections could be induced by inflammasome-mediated pyroptosis and interleukin-1β (IL-1β) released to further promote tumor development." (PMID 36276158, 2022). "IL-1β could promote bone colonization of metastatic tumor cells through transforming the bone stroma into a niche." (PMID 36237303, 2022). "In addition, multiple signaling pathways are activated as a result of the IL-1β stimulation of tumor cells, such as the PKB, MAPK, and NF-κB pathways." (PMID 36430487, 2022). "A previous study in BC revealed that the monocytes in the tumor microenvironment (TME) could be collected by IL-1β and further regulated the tumor cells proliferation." (PMID 36276158, 2022). "The effects of IL-1β have not only been addressed on tumor immunotherapy, however." (PMID 36144933, 2022). "As such, treatment of wild type mice with anti-IL-1β and anti-PD-1 was able to synergistically inhibit tumor progression, suggesting that adjuvant IL-1 inhibition could improve BCa patient response to immunotherapy." (PMID 35626710, 2022). "IL-1β can also be secreted by immune, stem, and tumor cells." (PMID 35884974, 2022). "The IL-1β inhibitor is known to increase the anti-tumor efficacy of 5-FU." (PMID 36140220, 2022). "IL-1β, as a class of pleiotropic pro-inflammatory cytokines, plays a key role in tumor development." (PMID 35513871, 2022). "This phenomenon depends on tumor cells activating the NLRP3 inflammasome to produce IL-1β." (PMID 36248807, 2022). "In B16F-10 melanoma cells, andrographolide inhibits the expression of granulocyte-macrophage colony-stimulating factors and pro-inflammatory cytokines such as TNF-α, IL-1β and IL-6 genes, inhibits the activation of NF-κB and AP-1 to promote apoptosis of tumor cells." (PMID 36238575, 2022).
tumor (continued). "Similar to IL-1β, IL-18 could also promote tumor progression by regulating the myeloid differentiation factor 88 (MyD88)/NF-κB signaling pathway." (PMID 36237303, 2022). "On one hand, this secretome could be deleterious, as IL-1β might increase vascular permeability, and IL-6 could inhibit dendritic cells (DCs), support tumor cell migration, and, just like IL-8, is able to promote tumor growth." (PMID 35563820, 2022). "Interestingly, IL1β appears to regulate anti-tumour immunity differently in the bone and soft tissue sites, promoting the recruitment of anti-tumour macrophages, neutrophils and Th1 cells in soft tissues and reducing myeloid cells in the bone." (PMID 36230739, 2022). "Indeed, previous studies found that the pro-tumorigenic role of IL-1β was also related to its ability to induce tumour cells to produce other cytokines, including IL-6." (PMID 35326545, 2022). "To test if TNFα or IL-1β cytokine signaling pathways were required to produce the robust anti-tumor immune response found when 5-FU is added to ICB, we administered TNFα or IL‐1β blocking antibodies throughout the 5-FU+ICB treatment schedule in AB1-HA tumor bearing mice." (PMID 35634282, 2022). "Many studies reported that IL-1β plays a pivotal role in tumor growth in CRC and its metastasis." (PMID 35954156, 2022). "Interestingly, IL-1β and NO can form a positive feedback loop: tumour cells and immune cells produce IL-1β, leading to the release of NO." (PMID 35869057, 2022). "IL-1β is another potent proinflammatory cytokine that is not only abundantly expressed within the tumor microenvironment of several cancers, but is also a key contributor to various aspects of cancer development, including tumor growth, angiogenesis and metastasis." (PMID 35757000, 2022). "Based on the role of interleukin-1β (IL-1β) in modulating the tumor microenvironment and further promoting tumor growth, the SPI1-IRF coactivating complexes might play a role in contributing to the formation of an inflammatory tumor microenvironment." (PMID 35664436, 2022). "In addition, IL-1β paradoxically enhances tumor progression by promoting an immune suppressive microenvironment with fewer IL-12 secreting dendritic cells." (PMID 35831470, 2022). "Nevertheless, a longitudinal measurement of IL-1β and IL-8 might serve as biomarkers to monitor tumor activity." (PMID 36294509, 2022). "IL-1β also increases resistance to apoptosis, potentially promoting tumor survival." (PMID 35038917, 2022). "The inflammasome-dependent cytokines IL-18 and IL-1β play a central role in anti-tumor immunity." (PMID 35517498, 2022). "Therefore, IL-1β neutralization or IL-1R blockade in tumor cells represents a direct targeted approach to reducing therapeutic resistance for cancer control." (PMID 36264639, 2022). "Additionally, etoposides’ action leads to the release of pro-inflammatory cytokines, such as IL-8, TNF-α, and IL-1β, which, depending on the tumor cell line, is inhibited by quinolones." (PMID 35756639, 2022). "In vitro and in vivo data have shown that IL-1β in particular promotes migration and invasion by cancer cells, triggers a more aggressive cancer phenotype, drives immunosuppression, and induces local tumor development and angiogenesis." (PMID 35086565, 2022). "Therapeutic strategies to mitigate neutrophil-CAF-tumor cell IL-1β/IL-6/STAT-3 signaling during NAC may improve pathologic responses and/or survival in PDAC." (PMID 36107485, 2022). "IL1β, IL-2, IL-12, TNF-α, and IFN-γ, known as Th1 cytokines, are associated with good prognosis in many malignancies, whereas Th2 cytokines (IL-4, IL-5, and IL-10) are associated with tumor growth and metastasis." (PMID 36090972, 2022). "A classic example is the nuclear factor kappa-light-chain-enhancer of activated B cells (NF-kB), a central transcription factor that is commonly activated in both tumor and immune cells to produce inflammatory cytokines, chemokines and growth factors, such as IL-1β, IL-6 and CCL2." (PMID 35757000, 2022).
tumor (continued). "These in vitro findings link efferocytosis of tumor AC and inflammasome-mediated IL-1β release in human macrophages to support our hypothesis." (PMID 36439171, 2022). "The reason for this is that IL1β is believed to exert its anti-tumour effects in the bone by inhibiting the expansion of the metastatic niche, bone resorption and the vicious cycle of bone metastasis, whereas IL1β promotes lung metastasis via reducing anti-tumour immune response." (PMID 36230739, 2022). "M2 TAMs facilitate HCC progression via producing protumor and proangiogenic factors and inhibiting tumor-infiltrating T cell activation, while M1 TAMs secrete IL1b, reactive oxygen species (ROS), and other pro-inflammatory cytokines to inhibit tumor progression." (PMID 36119533, 2022). "It is proposed that, in PC, the tumor-infiltrating PMN-MDSCs express upregulated IL-1β and IL-23a." (PMID 35860573, 2022). "In a colorectal cancer (CRC) model, macrophage-derived IL-1β was shown to elicit the production of serum amyloid A1 (SAA1) by tumor cells, which in a feed-forward manner induced macrophages to upregulate metalloproteinase-9 secretion allowing cancer migration and establishment of metastasis." (PMID 35517498, 2022). "At the molecular and cellular level, IL-1β supports tumor development by different mechanisms." (PMID 36293159, 2022). "Macrophage secretion of IL-1β was found to induce tumor expression of ICAM1." (PMID 36264639, 2022). "Overexpression of IL1β in tumour cells facilitates epithelial to mesenchymal transition (EMT), migration and invasion towards bone cells in vitro, as well as inducing bone homing properties and promoting the dissemination of tumour cells in the bone in in vivo models." (PMID 36230739, 2022). "During the process of tumor cell death, inflammation could be induced and related inflammatory cytokines such as TNF-α, IL-1β, and IL-6 further cause immune cell infiltration, which further results in the elimination of dead cells." (PMID 35402247, 2022). "Importantly, leukemic pyroptosis heightened CD8+ T cell immune function by releasing interleukin (IL)-1β/18 into the tumor microenvironment." (PMID 36316313, 2022). "In addition, tumor hypoxia induced an HIF-1α/IL-1β signaling loop between cancer cells and TAMs that leads to EMT in HCC." (PMID 36679900, 2022). "Notably, we also showed that pharmacological inhibition of NLRP3 with the inhibitor OLT1177 reduces IL-1β levels, ultimately reducing tumor progression." (PMID 35631400, 2022). "Furthermore, the expression of both IL-1β and IL-6, which have the ability to enhance the immune response against tumours by activating CD8+ T cells was also markedly increased." (PMID 35057796, 2022). "Apart from that, IL-1β inhibition acted in synergy with anti–PD-1 could lead to the restoration of the T cell-mediated tumor immunity for optimal tumor killing." (PMID 36119049, 2022). "Additionally, significant elevation of IL-1b expression in the healthy hemisphere was detected on day 21, corresponding to a fully regrown tumor." (PMID 35884700, 2022). "Moreover, ATO reduced IL-1β expression, with reduced IL-1β levels in tumor masses also observed on ELISA." (PMID 36264639, 2022). "IL-1B, as a member of the interleukin family, is closely related to tumor immunity." (PMID 36299603, 2022). "Tumor-derived IL-1β might also act via an IL-6-STAT3 inflammatory loop to expand MDSCs and induce immunosuppression." (PMID 35517498, 2022). "Moreover, tumor weight and growth were significantly promoted by IL-1β treatment yet further treatment of sh-lncRNA CHRF resulted in opposite results while further miR-489 inhibitor treatment played a vital catalytic role." (PMID 35711847, 2022). "In the inflammatory loop of T2DM homoeopathy, two factors, TNF-α and IL-1β, also occupy an important position, among which TNF-α tumor necrosis factor, which functions to cause tumor chemise necrosis and tumor cell death, has a wide range of biological activity." (PMID 35979044, 2022).
tumor (continued). "Besides TAMs, PDAC tumor cells also activate the Nlrp3 inflammasome and act as a prominent source of IL-1β." (PMID 35517498, 2022). "Under the influence of IL-1β, IL-8, and TGFβ, which can affect Wnt/β-catenin signaling, cancer cells can gain stem-like qualities and form a subpopulation of cancer stem cells capable of self-renewal and recreation of the entire tumor population." (PMID 35884974, 2022). "IL1β is a cytokine able to induce angiogenesis, tumor growth and metastasis." (PMID 36555441, 2022). "In the anti-tumor setting, culture of Th9 cells with IL-1β or cells with heightened NF-kB activity exhibited enhanced expression of the CD4 cytotoxic lymphocyte transcription factor Eomes and enhanced granzyme/perforin-associated killing after adoptive transfer." (PMID 36389679, 2022). "IL1B signaling has been well investigated in tumor angiogenesis ﻿." (PMID 36575469, 2022). "This clinical study provided strong evidence that IL-1β antagonism could prevent both the recurrence of cardiovascular events and tumor development in patients with a persistent pro-inflammatory response." (PMID 36104342, 2022). "Neutrophils are attracted to tumours by tumour-derived IL-1β, prostaglandin E2 (PGE2), and IL-8." (PMID 35260891, 2022). "However, IL-1β also enhances the anti-cancer ability of tumor-specific T cells in B16 melanoma tumors in mice." (PMID 35856558, 2022). "Whereas IL-10 inhibit LCs migration, IL-1β contribute to their proliferation and their pro-tumourigenic cytokine network is stimulated leading to tumour pathogenesis through the dysregulation of signalling pathways in human dysplastic oral keratinocytes (DOK), as demonstrated in OSCC cells." (PMID 35406451, 2022). "In addition to SDF-1, fibroblast-derived IL-1β/IL-6, tumor cell-derived-IL-8, and tumor-infiltrated lymphocyte-derived-TNF-α were upregulated in OSCC patients with high TNM stage." (PMID 36045118, 2022). "Moreover, quercetin decreased IL-6/IL-1β in the rats with early HCC for initiating the immune response to kill tumor cells." (PMID 36615387, 2022). "We identified that IL1B, specifically expressed by a subset of tissue-resident macrophage cells, could potentially promote tumor cells undergoing EMT, with both cell types found to be enriched at the tumor-normal interface." (PMID 36423636, 2022). "As an important molecular marker of pyroptosis, IL1β is generally released from the pore formed by oligomerized GSDMD and has been shown to be closely associated with the formation of an immunosuppressive microenvironment in several tumor types." (PMID 36199426, 2022). "Moreover, NO, as a soluble factor produced by TA-MSCs, has been shown to enhance etoposide resistance in pancreatic tumours in vitro, and IL-1β from tumour cells is an effective stimulator that increases the release of NO." (PMID 35869057, 2022). "We further employed several transgenic mouse strains and adoptive bone marrow transfer experiments to show that effective pharmacologic KRAS blockade in vivo is dependent on the presence of CCR2+ (C-C motif chemokine receptor 2) IL-1β-secreting myeloid cells in the tumor microenvironment." (PMID 35327394, 2022). "The function of IL-1β in the TIME is a double-edged sword in tumor progression." (PMID 35739593, 2022). "Analysis of flash-frozen whole-tumour lysate revealed substantial levels of IL-1α, IL-1β and IL-18." (PMID 35545675, 2022). "Furthermore, several anti-tumor agents were shown to induce IL-1β mostly in a NLRP3 inflammasome–dependent manner; therefore, the treatment of tumors with the combination of conventional agents and anti-IL-1β has been adapted." (PMID 35739593, 2022). "IL-1β promoted immunosuppression by recruiting neutrophils to the tumor bed." (PMID 35517498, 2022). "As Th9 cells play important roles in auto- and anti-tumor immunity, our studies suggest that therapeutic targeting IL-1β/IL-1R1 signaling may be beneficial in dampening Th9-mediated inflammation or may be bolstered to enhance tumor clearance." (PMID 36389679, 2022).
tumor (continued). "Notably, in BC tissue, Th17 cells are positively related to the IL-6, IL-1β, and IL-17 expression, and also negatively correlated with an increase in the number of metastatic lymph nodes and angiogenesis of tumor cells as well." (PMID 35248028, 2022). "Our reasoning for this is that we have previously demonstrated that IL1β has opposing effects on tumour growth in the bone compared with soft tissue and that these differences in pro/anti-tumour effects are driven by differential, site-specific, immunological responses." (PMID 36230739, 2022). "In addition, other factors such as VEGF, TGF-β, IL-1β, IL-13, Granulocyte-macrophage colony-stimulating factor (GM-CSF) and prostaglandins produced by tumour cells (and other cells of the TME), impact in DCs differentiation and/or maturation." (PMID 35406451, 2022). "Interestingly, IL1B was specifically expressed by TR Mac.2, which again was enriched at the tumor-normal interface." (PMID 36423636, 2022). "Several clinical trials for anti-IL-1β or IL-1R blockage in tumor treatment are ongoing." (PMID 35739593, 2022). "In addition, inhibition of IL-1β in RCC has been shown to induce tumor regression in a syngeneic murine model of RCC." (PMID 36423636, 2022). "Likewise, It was shown that inflammasome and IL1β are involved in tumor growth and metastasis and IL1 receptor antagonist significantly inhibited tumor growth and metastasis in the mice model of lung cancer." (PMID 35527284, 2022). "Tumor-derived IL-1β inhibits tumor growth and enhances survival through host responses." (PMID 35632758, 2022). "IL-1β promotes tumor growth in a Lewis lung carcinoma model by upregulating VEGF and CXCL2." (PMID 35626056, 2022). "Subsequently we showed that NLRP3-mediated IL-1β production drives tumor growth in vivo." (PMID 36439171, 2022). "Furthermore, pyroptotic cells release pro-inflammatory cytokines such as IL-1β and IL-18 along with various DAMPs that prime an auxiliary anti-tumor immune response." (PMID 36376979, 2022). "On the one hand, pyroptosis alters the tumor microenvironment and inhibits tumor growth by releasing inflammatory factors such as IL-1β and IL-18; on the other hand, pyroptosis reduces the immune responses of the body to tumor cells and accelerates the growth rate of different cancers." (PMID 36142404, 2022). "M2 macrophage behaviour exists more heterogeneously and can be triggered by IL-4 or IL-13, IL1-β, TGF-β, IL-6, phagocytosis of apoptotic cells, or association with a tumour microenvironment, respectively, generating M2a, M2b, M2c, M2f, and tumour-associated macrophages (TAM)." (PMID 36254592, 2022). "Likewise, orthotopic injection of 4T1 BCa cells into IL-1β knockout mice formed tumors that regressed, had reduced immunosuppressive macrophage infiltration and activation, and favored anti-tumor dendritic cell infiltration." (PMID 35626710, 2022). "The role of IL-1β in tumor progression is partially due to its effect on immune cells in the TME." (PMID 35086565, 2022). "Moreover, in HCC, TAMs are more prone to fatty acid oxidation, a characteristic that promoted tumor cell migration in vitro via IL-1β." (PMID 36551635, 2022). "Specifically, MyD88 (IL-1β) was significantly increased compared the TM + T group which may indicate preconditioned exercise is able to protect against tumor-mediated cardiac inflammation that may serve to protect the heart." (PMID 36531941, 2022). "There was a very low level of IL-1β produced by normal and tumor cells." (PMID 35335367, 2022). "Furthermore, proinflammatory cytokines, such as TNF-α, IL-6, and IL-1β, secreted by activated cells are known to be involved in the destruction of pathogens and tumor cells." (PMID 36422317, 2022). "Inhibition of IL-1β reduces tumor invasiveness, thus pointing to its utility in cancer therapy." (PMID 35511379, 2022).